DOCK9 (dedicator of cytokinesis 9)
Description:
Guanine nucleotide-exchange factor (GEF) that activates CDC42 by exchanging bound GDP for free GTP. Overexpression induces filopodia formation.
Synonyms: KIAA1058; ZIZ1; ZIZIMIN1
Tractability: Small molecule: a structure with a bound ligand is known; it has a binding pocket of medium quality. PROTAC: ubiquitination databases record sites on it; its protein half-life has been measured.
Gene: Protein-coding gene on chromosome 13 (98,793,429 to 99,086,625, reverse strand). Ensembl gene ENSG00000088387.
Subcellular location: Endomembrane system
Pathways (Reactome):
Signal Transduction: CDC42 GTPase cycle; RAC1 GTPase cycle
Hemostasis: Factors involved in megakaryocyte development and platelet production
Gene Ontology:
Molecular function: cadherin binding; protein binding; guanyl-nucleotide exchange factor activity
Biological process: positive regulation of GTPase activity; regulation of Rho protein signal transduction; small GTPase-mediated signal transduction
Cellular component: membrane; cytosol; endomembrane system
Genetic constraint (gnomAD): Loss-of-function variants: 76 observed, 216.36 expected, observed/expected ratio (o/e) 0.35, 90% interval 0.29 to 0.43. The upper end of that interval is the gene's LOEUF score, 0.43, which puts it in group 1 of 6, group 1 being the genes least tolerant of losing a copy. Missense variants: 1,934 observed, 2,398.7 expected, observed/expected ratio (o/e) 0.81, 90% interval 0.78 to 0.84. Synonymous variants: 911 observed, 903.31 expected, observed/expected ratio (o/e) 1.01, 90% interval 0.95 to 1.07.
Homologues: Orthologues: macaque DOCK9 (98% identical), chimpanzee DOCK9 (97% identical), mouse Dock9 (95% identical), dog DOCK9 (95% identical), guinea pig DOCK9 (95% identical), pig DOCK9 (94% identical), rabbit DOCK9 (94% identical), rat Dock9 (94% identical), tropical clawed frog dock9 (87% identical), zebrafish dock9b (75% identical), zebrafish dock9a (66% identical), Drosophila melanogaster Zir (28% identical), and 2 more. Paralogues in human: DOCK11 (59% identical), DOCK10 (54% identical), DOCK6 (30% identical), DOCK8 (30% identical), DOCK7 (30% identical), DOCK3 (15% identical), DOCK1 (15% identical), DOCK5 (15% identical), DOCK2 (14% identical), DOCK4 (14% identical).
Diseases named in the same sentence as DOCK9 in open-access papers:
DOCK9 is named in the same sentence as 34 diseases in open-access papers, as found by Europe PMC text mining. Sharing a sentence is not in itself a finding about the gene and the disease. The quoted sentences say what the papers report.
Anxiety (3 papers, 2021 to 2023). Intense feelings of nervousness, tension, or panic often arise in response to interpersonal stresses. "Interestingly, the largest GWAS study identified six genetic susceptibility loci that were significantly associated with IBS, four of which were located in genes associated with mood and anxiety (NCAM1, CADM2, PHF2/FAM120A, DOCK9)." (PMID 36071849, 2022).
schizophrenia (3 papers, 2013 to 2025). A major psychotic disorder characterized by abnormalities in the perception or expression of reality. "HMSE associated DAOA and visuospatial span associated DOCK9 have been linked to bipolar disorder and schizophrenia." (PMID 40665476, 2025). "These include GFOD1, which is associated with attention deficit hyperactivity disorder (ADHD), DLGAP1 which is associated with schizophrenia, DOCK9 associated with bipolar disorder, and SORCS1 which is associated with memory." (PMID 24151499, 2013). "Pericytes were the second cluster with the highest number of DEGs between schizophrenia and controls, with increased LRBA and reduced DOCK9 expression activity in schizophrenia pericytes." (PMID 36192459, 2022). "The reduced expression of DOCK9 in the pericytes of schizophrenia cases could affect the structure of the brain blood vessels, and this might not necessarily be reflected in the transcriptome of the vasculature." (PMID 36192459, 2022). "In contrast to reduced DOCK9, the expression of LRBA was higher in schizophrenia pericytes compared to controls." (PMID 36192459, 2022).
breast carcinoma (2 papers, 2019 to 2024). "Intercalation and adhesion assays showed that breast cancer cells depleted of DOCK9 adhere to BEC as efficiently as control cells; however, they show a significant delay in intercalation compared to control cells at the time point where ≥ 50% control cells have intercalated (T50)." (PMID 38762624, 2024). "We also show that brain endothelial cells promote paracrine stimulation of mesenchymal-like morphology of breast cancer cells via DOCK4, DOCK9, RAC1 and CDC42." (PMID 38762624, 2024). "Altogether, our data suggest that the brain endothelium and EGF contribute to extravasation by promoting DOCK4/RAC1- and DOCK9/CDC42-mediated elongation and intercalation of breast cancer cells." (PMID 38762624, 2024). "Hence, we investigated the role of DOCK9 and CDC42 in elongation and intercalation of breast cancer cells." (PMID 38762624, 2024). "Hence, BEC promote metastatic extravasation through activation of EGFR signalling in breast cancer cells that requires DOCK4, DOCK9, RAC1 and CDC42, rendering them competent for extravasation." (PMID 38762624, 2024). "Elongation assays showed that, like DOCK4-depleted cells, cells lacking either DOCK9 or CDC42 did not elongate upon EGF stimulation as control cells, suggesting that DOCK9 and CDC42, together with DOCK4 and RAC1, are essential for the elongation and subsequent intercalation of breast cancer cells." (PMID 38762624, 2024).
keratoconus (2 papers, 2014 to 2023). A degenerative, structural disorder of the eye, characterized by a cone-shaped protrusion of the cornea. "However, using this approach in large extended pedigrees has led to the identification of two potential genes (MIR184 and DOCK9) associated with keratoconus." (PMID 25254113, 2014). "A recent study in Polish patients with sporadic keratoconus, however, reported that keratoconus-related sequence variants in these genes (DOCK9, IPO5, and STK24) were present only in small number of studied patients indicating that these genes may have minor roles to play." (PMID 25254113, 2014). "Missense variants in heterozygosis in genes described to be associated with keratoconus were detected in the proband: EML6, which appears in the OFT-00817 and OFT-00851 families and whose implication has been previously reported, and DOCK9 (OMIM: #607325)." (PMID 37895187, 2023). "Family-based studies have led to the identification of MIR184 and DOCK9 genes in cases with familial keratoconus; however, the replication of locus identified in a specific keratoconus family in other families (even in homogeneous population) has been very limited." (PMID 25254113, 2014).
osteoporosis (2 papers, 2022 to 2023). A condition of reduced bone mass, with decreased cortical thickness and a decrease in the number and size of the trabeculae of cancellous bone (but normal chemical composition), resulting in increased fracture incidence. "While the other CSN network gene with higher association in the HO group, DOCK9, is not a predictive feature for osteoporosis in postmenopausal females." (PMID 37051201, 2023). "In summary, this paper proposed that IRF4/miR-636/DOCK9 may be considered as targets for the treatment of osteoporosis (OP)." (PMID 35397366, 2022). "Furthermore, the downstream target genes of miR-636 were identified, and the effect of IRF4/miR-636/DOCK9 on osteogenic differentiation was investigated for the treatment of osteoporosis." (PMID 35397366, 2022). "In summary, IRF4/miR-636/DOCK9 axis was a promising target for the treatment of osteoporosis." (PMID 35397366, 2022). "Few studies have reported the role of DOCK9 in osteoporosis." (PMID 35397366, 2022).
brittle cornea syndrome (1 paper, 2023). Brittle cornea syndrome is a form of Ehlers-Danlos syndrome characterized by a severe ocular manifestations due to extreme corneal thinning and fragility with rupture in the absence of significant trauma, and progression to blindness. "Genes that stand out include VSX1 for its role in posterior polymorphous dystrophy (PPCD); ZNF469, implicated in brittle cornea syndrome and central corneal thinning (CCT); and DOCK9 or Zizimin1, associated with corneal ectasia." (PMID 37895187, 2023).
irritable bowel syndrome (1 paper, 2025). Irritable bowel syndrome (IBS) is a chronic functional condition of the lower gastrointestinal (GI) tract characterized by abdominal pain or discomfort and disordered bowel habit (diarrhea, constipation, or fluctuation between the two). "For example, in a genome-wide association study (GWAS) of 53,400 people with irritable bowel syndrome, DOCK9 was associated with mood and anxiety disorders." (PMID 41159936, 2025).
lung carcinoma (1 paper, 2023). "The function and mechanism of DOCK9 in lung cancer, remain more experiments to investigate." (PMID 37477536, 2023).
tuberculosis (1 paper, 2016). A chronic, recurrent infection caused by the bacterium Mycobacterium tuberculosis. "Thus, further studies are needed to assess whether different M. tuberculosis strains, infection sites, previous infections, host genetic background or co-morbidities can affect DOCK9 and EPHA4 mRNA expression profiles." (PMID 27826286, 2016).
cancer (3 papers, 2016 to 2022). A tumor composed of atypical neoplastic, often pleomorphic cells that invade other tissues. "As a first step, we chose to study DOCK4 and DOCK9 among a large family of GEFs, given that DOCK4 and DOCK9 have been demonstrated to respectively activate Rac1 and Cdc42 and that mutations in DOCK4 and DOCK9/Zizimin1 have been found in a number of cancers." (PMID 32143485, 2020). "Knockdown of DOCK4 and DOCK9 was also reported to reduce cancer growth." (PMID 32143485, 2020).
cardiovascular disease (1 paper, 2013). "At 4 weeks post-MI, 4 genes (DOCK9, MBNL1, RRAD, and ZSWIM6) by all of 37 unique altered transcripts were related to cardiovascular disease." (PMID 23372767, 2013).
immune disorders (1 paper, 2025). "Dedicator of cytokinesis 9 (Dock9), which plays a role in immune disorders, showed a decrease in mRNA expression in TLY012-treated mice." (PMID 39808500, 2025).
tumour (1 paper, 2020). "KALRN, MCF2/Dbl, NGEF/EPHEXIN, ARHGEF7/βPix/COOL-1, CDC42EP2, DOCK9, NET1, TIAM2, ABR, PLEKHG5, RhoBTB2 and PREX1 were identified as being increased at the tumour rim." (PMID 33256106, 2020).
DOCK9 also shares sentences with these, for which no sentence is quoted: anxiety disorder (2 papers); autism (2); bipolar disorder (2); acute respiratory distress syndrome (1); anorexia nervosa (1); arteriopathy (1); attention deficit-hyperactivity disorder (1); cervical cancer (1); depression (1); developmental delay (1); epilepsy (1); heart failure (1); hepatocellular carcinoma (1); infarction (1); microcephaly (1); mood disorder (1); neurodevelopmental disorder (1); Obesity (1); ovary cancer (1); Sepsis (1); soft tissue sarcoma (1).